CD4 (CD4 molecule)
Diseases named in the same sentence as CD4 in open-access papers (continued):
Sharing a sentence is not in itself a finding about the gene and the disease.
influenza (continued). "While ILC2s were present earlier in the lung than T cells, their numbers did not increase due to influenza infection, and CD4 + T cells were able to produce pathogenic type 2 cytokines earlier during influenza-induced asthma exacerbation." (PMID 33101299, 2020). "In general, CXCR5, compared to CXCR3 and CCR6, is the chemokine receptor that was most prominently expressed on tetramer-positive cells with mean levels of up to 40% for citrulline-specific and 54% for influenza-specific populations while for the general CD4+ population it was only around 10%." (PMID 32423478, 2020). "However, our data show that even when a split influenza vaccine is administered at 4X the normal dose (Fluzone HD), the split vaccine still performed less well than did Flublok in eliciting CD4 T cells." (PMID 32884842, 2020). "A better understanding of the role of CD4+ T cell responses is needed for novel influenza vaccines." (PMID 32183105, 2020). "However, the administration of a detergent split influenza antigen adjuvanted with a TLR4 ligand CRX-601 intranasally led to the induction of harmful antigen specific CD4+TNFα+Th17+ cells in mice." (PMID 33391267, 2020). "Also, as expected for patients not subject to ongoing infections or recent vaccination, the level of expression on the influenza-specific control as well as the general CD4+ population was very low for both these markers." (PMID 32423478, 2020). "Though some evidence suggests that preexisting influenza-specific CD4+ T cells correlate with disease protection in an influenza human challenge model, other studies have shown that baseline CD4+ T cell responses negatively correlate with antibody response after influenza vaccine." (PMID 32183105, 2020). "To address this important issue, we recently we formally compared CD4 T cell epitope selection in mice via influenza infection vs. vaccination with recombinant NP and HA revealed that the multitude of individual NP and HA epitopes elicited by these two modes of priming were the same." (PMID 31694141, 2019). "Higher net levels of CD4+ T cells in women relative to men may, therefore, significantly affect an individual's ability to respond effectively to influenza vaccines." (PMID 30873150, 2019). "Interestingly, within in vitro systems we further identified that increased propionic acid supported ex vivo proliferation of influenza-specific CD4+ and CD8+ T cells." (PMID 31050747, 2019). "With the help of advances in computational studies and data science, it may be possible to identify predictable events confronting the immune system that perturb and ultimately control the repertoire of CD4 T cells specific for influenza." (PMID 31134060, 2019). "However, there is little known about how these early childhood influenza exposures shape CD4 T cell reactivity later in life." (PMID 30692574, 2019). "Finally, a protocol was established to investigate the extent to which FoxP3+ regulatory CD4 T cells impact the outcome of primary and heterosubtypic influenza infection." (PMID 30641955, 2019). "Here, we consider the events that prime and remodel the influenza-specific CD4 T cell response in humans that have highly diverse immune histories and how the CD4 repertoire may be edited in terms of functional potential and viral epitope specificity." (PMID 31134060, 2019). "In our study, we have demonstrated that BM CD4+ TSCMs that could help the maturation of antibodies against influenza were very important for anti-influenza immune." (PMID 30733641, 2019). "In addition, these findings have revealed the relationship between BM CD4+ TSCMs and anti-influenza immunity." (PMID 30733641, 2019). "This may ultimately limit the specificity of CD4 T cells to highly diverse HA proteins, diminishing cross protection against diverse influenza strains." (PMID 31134060, 2019). "Indeed, TRM CD4+ cells appear to be a good marker for protection from morbidity and mortality in murine models of influenza infection." (PMID 31700523, 2019).
influenza (continued). "TRM CD8+ T cells may be critical in viral clearance and TRM CD4+ cells are also thought to be important for influenza protection." (PMID 31700523, 2019). "The broad reactivity of these CD4 T cells could allow them to provide cross-reactive immunity against many influenza strains, particularly if their functional and lung homing potential induced by the original infection is maintained." (PMID 31134060, 2019). "When there was influenza infection, Tfr cells was approximately 5–8% of CD4+CXCR5+ cells." (PMID 31382877, 2019). "Furthermore, compared to spleen-resident CD4+ TSCMs, BM-resident TSCMs induced the production of high-affinity antibodies against influenza by B lymphocytes more efficiently." (PMID 30733641, 2019). "Finally, the fifth model we will discuss addressed the role of CD4+ FoxP3+ regulatory cells (Treg) during influenza infection by treating WT mice with anti-CD25 antibody (clone PC62) to deplete this subset prior to infection." (PMID 30641955, 2019). "If childhood exposure is uniquely capable of imprinting specificity and functionality the immune system, then these early exposures to influenza primarily through vaccination might prime a limited CD4 repertoire." (PMID 31134060, 2019). "Indeed, pre-existing influenza-specific CD4+ T cells were recently shown to protect against symptomatic illness in both H3N2 and H1N1 human challenge studies." (PMID 31166987, 2019). "In addition, CD4 T cells demonstrated a necessary role during influenza vaccinations and provided cross-protective anti-influenza immune responses." (PMID 31683888, 2019). "This indicates that the autosomal-iSEXS score detects sex differences in the dynamics of the immune response to influenza infection, which may be explained by sex differences in CD4+ T cell proportions." (PMID 31722210, 2019). "Several recent publications suggested that influenza infection might select for a distinct set of CD4 epitopes than those elicited by vaccination through a pathway initiated by infected antigen presenting cells." (PMID 31694141, 2019). "The administration of trivalent split-virus influenza vaccines was shown to induce the temporary accumulation of circulating ICOS+ CXCR3+ CXCR5+ CD4+ T cells, and up to 60% of these cells were specific for influenza antigens and correlated with an increase in preexisting antibody titers." (PMID 31300682, 2019). "For example, if early-life exposures to influenza do effectively imprint the specificity and function of CD4 T cells, vaccines that establish the most robust and diverse repertoire of T cells may be most critical for infants and young children." (PMID 31134060, 2019). "Although our data have demonstrated that the BM CD4+ TSCMs could help the maturation of antibodies against influenza produced by B cells, it remained unknown whether BM CD4+ TSCMs could help B cell-secreted antibodies against other fatal diseases." (PMID 30733641, 2019). "Differentiation decisions during CD4 T cell priming have been attributed to the local microenvironment, particularly cytokines, but in the case of influenza infection, and dominant Th1 biased response, many other distinct functional subsets of CD4 T cells quickly emerge." (PMID 31134060, 2019). "Here we consider the potential impact of CD4 T cell imprinting and editing of the human CD4 T cell repertoire to influenza and the potential consequences this might have on protective immunity to infection." (PMID 31134060, 2019). "In an influenza challenge model, mice that received adoptive transfer of lung memory CD4+ T-cells exhibited only minor symptoms and complete lung viral clearance by day 8 post infection, compared to naïve mice or those receiving spleen memory CD4+ T-cells, in whom the infection was lethal." (PMID 31130965, 2019). "Work investigating the HIV reservoir has indicated circulating CD4+CD32+ T cells may be of interest in responses arising from B cell interactions such as the reaction to inactivated influenza vaccination." (PMID 31666568, 2019).
influenza (continued). "In contrast, CD4 T cells recognize a wide array of epitopes, with specificities that are heavily influenced by the diversity of influenza antigens available, and a multiplicity of functions that are determined by both priming events and subsequent confrontations with antigens." (PMID 31134060, 2019). "We identified differences in both the specificity and functionality of influenza-specific CD4 T cells between these subject cohorts, with children having less elaboration of IFNγ upon antigenic stimulation and decreased immunodominance of the internal virion proteins when compared to adults." (PMID 30692574, 2019). "We observed sex differences in the dynamics of CD4+ T cell proportions during influenza infection." (PMID 31722210, 2019). "However, new data revealed CD4+ memory specific to highly conserved internal influenza virus proteins as a protection correlate in human influenza infection." (PMID 31019503, 2019). "Because of our interest in the full potential repertoire of influenza-specific CD4 T cells, our laboratory has used unbiased epitope scanning methods to identify the entire array of peptides recognized by CD4 T cells in the primary response in mice to influenza infection or vaccination." (PMID 31694141, 2019). "These CD4+ T cell responses are induced in the weeks after influenza vaccination and may be better predictors of long-term immunity in healthy adults than other measures of immunity." (PMID 30873150, 2019). "Thus, by many different mechanisms, CD4 T cells specific for influenza viral antigens are established early in life." (PMID 31134060, 2019). "However, there is much less known about influenza-specific CD4 T cell specificity and function in children." (PMID 30692574, 2019). "In the case of influenza vaccination, memory CD4 T cells have been shown to recognize conserved viral glycoproteins and may be able to provide cross-protective (heterotypic) protection to multiple influenza strains." (PMID 30386342, 2018). "Broadly protective immunity against influenza can be provided by memory CD4 and CD8 T-cells." (PMID 30138320, 2018). "A comparison of two different licensed influenza vaccines given by intranasal or parenteral routes demonstrated that the route of administration, as well the type of vaccine (live versus killed), influenced the induction of CD4 TRM cells." (PMID 30147701, 2018). "Furthermore, only HA-specific CD4 TRM cells from the lungs conferred protection against lethal influenza infection." (PMID 30147701, 2018). "An IL-2 independent pathway for CD4 TRM generation has also been identified in influenza infection." (PMID 30386342, 2018). "Similarly, a recent study showed that emergence of plasmablasts and ICOS+CXCR3+CXCR5+CD4+ T cells in blood peaked on day 7 after influenza vaccination." (PMID 30055570, 2018). "In the case of influenza infection, the presence of iBALT is correlated with accelerated secondary CD4 T cell responses, suggesting that iBALT might provide a survival niche for Th1 TRM." (PMID 30386342, 2018). "Furthermore, it is clear from influenza mouse models that CD4+ T cell help is required for the promotion of CD103+ CD8+ Trm cells and so both play an important part in the induction of heterosubtypic immunity." (PMID 29552008, 2018). "A previous study demonstrated that the activation of CD4+ T cells (Th1) by influenza vaccination leads to the secretion of Th1-type cytokines (e.g., interferon-γ), which activates macrophage phagocytosis and may subsequently kill intracellular M. tuberculosis." (PMID 29460733, 2018). "In this study, we have evaluated whether the diverse CD4 T cell epitope specificity that is elicited in the lung dLN after influenza infection persists in the CD4 T cells that home to the lung." (PMID 29681900, 2018).
influenza (continued). "However, continued efforts using adapted methods such as peptide scanning or whole virus for identification of influenza-specific CD4+ T cells have revealed their intrinsic necessity for heterologous protection against influenza virus infection." (PMID 29587436, 2018). "While human studies have corroborated the findings in murine studies regarding the importance of CD4+ T cells to flu vaccine and memory CD4+ T cell responses, the importance of the different subsets has yet to be investigated in elderly humans during flu infection." (PMID 29616390, 2018). "Collectively, these studies suggest that influenza-specific CD4 T cells that home to the lung after infection can encounter peptide:MHC class II complexes and such contact might affect survival and potential remodeling of the immunodominance hierarchy." (PMID 29681900, 2018). "In a transgenic mouse model, CD4+ T cells have also been found to be directly cytotoxic during influenza infection, and human influenza-specific CD4+ T cells can express granzymes, perforin, IFN-γ, and exhibit killing function correlating with reduced severity of infection and viral loads." (PMID 29587436, 2018). "Using a mouse model of influenza A H1N1 infection and an unbiased method to identify CD4 T cell epitopes elicited by influenza infection, we compared the diversity of influenza-specific CD4 T cells and immunodominance hierarchies within the lung with that established in the priming lymph node." (PMID 29681900, 2018). "In addition, little is known about CD4+ epitope variation during influenza infection due to a paucity of defined epitopes." (PMID 29587436, 2018). "Interestingly, combining whole virion influenza and whole cell pneumococcal vaccine also promoted the generation of lung CD4+ TRM." (PMID 30038624, 2018). "Whether influenza viral antigens are accessible in the form of peptide:class II complexes to infiltrating CD4 T cells and persists as the adaptive response progresses in the infection model studied here is not known." (PMID 29681900, 2018). "Thus, novel cross-protective influenza vaccines should be capable of efficiently inducing not only antibodies to conserved influenza antigens, but also cross-protective T-cell responses (CD4+ and CD8+)." (PMID 29631629, 2018). "A similar relationship has been found for CD4+IFNγ− producing T cells specific to influenza." (PMID 29866115, 2018). "Finally, cellular responses are critical for recovery from and memory against virtually all viral pathogens and natural influenza infection elicits strong CD4+ and CD8+ T cell responses." (PMID 29252098, 2018). "Both CD4+ and CD8+ T cells have been associated with less severe influenza in humans." (PMID 28368530, 2017). "Finally, our studies revealed that many different types of influenza antigen-bearing cells express MHC class II proteins at the cell surface and differ in their capacity to re-stimulate influenza-specific CD4 T cells ex vivo." (PMID 28883436, 2017). "R620W-associated defects in CD4 T cell response to influenza vaccination recently observed by our group were not reproduced in this study." (PMID 28723925, 2017). "Thus, pre‐existing cross‐reactive CD4 T cells can be a limiting factor in the generation of protective antibody titres to influenza proteins." (PMID 28146323, 2017). "Because a subset of these cells display viral peptide:MHC class II complexes and can stimulate influenza-reactive CD4 T cells, they have the potential to interact with previously activated, resident or newly primed CD4 T cells that migrate to the lung after expansion and differentiation." (PMID 28883436, 2017). "Similar CD4 CTL responses are induced in humans following seasonal influenza vaccination." (PMID 28167943, 2017). "Importantly, we have identified and confirmed that multiple Venuspos cell subsets in the lung can stimulate influenza-reactive CD4 T cells, which appeared to differ based on infection status, lineage and MHC class II molecule expression." (PMID 28883436, 2017).
influenza (continued). "Finally, differences in infection status, cell lineage and MHC class II expression by antigen-bearing cells correlated with differences in their ability to re-stimulate influenza-specific CD4 T cells ex vivo." (PMID 28883436, 2017). "Among healthy non-pregnant adults, we found that R620W carriage associated with a fold-change expansion of circulating influenza-specific CD4 T cells approximately half that observed in non-carriers." (PMID 28723925, 2017). "We found that the neutralizing antibody titer increased about 5.6 fold in mice with previously established HA-specific CD4 T cell memory when compared to sham-immunized mice that underwent a secondary influenza infection, from a geometric mean of 25.4 to a geometric mean of 143.7." (PMID 28493882, 2017). "It is well established that CD8+ CTLs play a crucial role in the response to influenza infection, as demonstrated in both mouse models and humans, while the relationship between influenza-specific CD4+ T cells and disease protection and limitation was investigated only in recent years." (PMID 28289418, 2017). "However, the seasonal influenza vaccine is poor at inducing CD4(+) T-cell responses and needs to be combined with an adjuvant facilitating this response." (PMID 29358939, 2017). "Similarly, the efficacies of vaccines against other newly emerging influenza subtypes are expected to be related to the presence of cross-reactive CD4+ memory T cells that are generated by seasonal viruses and/or vaccines." (PMID 28455520, 2017). "There was limited induction of IL‐2 from CD4+ T cells, which could, in part explain the paucity of CD4+ T‐cell‐dependent NK‐cell responses on re‐stimulation with influenza antigen in vitro." (PMID 28383105, 2017). "We evaluated the role of PTPN22 R620W carriage in CD4 T cell responses to influenza vaccination." (PMID 28723925, 2017). "Influenza-specific memory T cells are highly cross-reactive; CD4 and CD8 epitopes are specific for the conserved protein sequences across different influenza strains and, thus, do not depend on an exact match of the vaccine strain with the circulating strain of influenza virus." (PMID 26941738, 2016). "However, a detailed viral dynamics study of the role of CD4+ T cells in influenza infection, including in HIV-infected patients with depleted CD4+ T cells, remains an open and important challenge." (PMID 28066421, 2016). "Inactivated and recombinant influenza vaccines induce a robust antibody and CD4 T cell response." (PMID 27177221, 2016). "With the ability to detect the six selected epitopes of interest in a single staining tube, we designed and executed a proof-of-principle study to characterize changes in influenza-specific CD4+ T-cell responses elicited by the 2014–2015 northern hemisphere seasonal influenza vaccine." (PMID 27571776, 2016). "The first is whether different specificities of influenza-reactive CD4 T cells convey different functions." (PMID 26834750, 2016). "Interestingly, we found that in both the total CD4 T cell population and the influenza NP-specific CD4 T cell population there was a significant skewing towards a Tfh phenotype in aged groups." (PMID 27177221, 2016). "Since antigen-specific CD4+ T cells can also have a role in mediating protection by contributing to the development of the effector functions of CD8+ T cells, we characterized lung NP- and M1-specific CD4+ T cells after vaccination and subsequent influenza infection." (PMID 27525409, 2016). "Importantly, antigen-specific IL-6Rα+IL-7R+ CD4+ T cells emerge from the effector population at late time points post influenza infection." (PMID 26743592, 2016). "Existing data suggest that routine encounter with seasonal influenza through infection or vaccination regularly boosts CD4 T cells of many specificities, establishing memory cells that can cross-reactively recognize epitopes specific from potentially pandemic strains." (PMID 26834750, 2016).